RUNX2 (RUNX family transcription factor 2)
Diseases named in the same sentence as RUNX2 in open-access papers (continued):
Sharing a sentence is not in itself a finding about the gene and the disease.
mesenchymal chondrosarcoma (1 paper, 2023). A morphologic variant of chondrosarcoma arising from bone and soft tissue. "HEY1-NCOA2 is associated with RUNX2 in mesenchymal chondrosarcoma." (PMID 37212282, 2023). "Runx3, which is also expressed in mesenchymal chondrosarcoma and interacts with HEY1-NCOA2, replaced the DNA-binding property of Runx2 only in part." (PMID 37212282, 2023). "Collectively, these results underscore the role of Runx2 and its interaction with HEY1-NCOA2 in disease phenotypes of mesenchymal chondrosarcoma." (PMID 37212282, 2023).
Metopic synostosis (1 paper, 2010). Premature fusion of the metopic suture. "We identified a heterozygous inverted duplication of 6p12.3-p21.1 encompassing the RUNX2 gene in two individuals with metopic synostosis." (PMID 20683987, 2010).
myelofibrosis (1 paper, 2022). A partial or complete replacement of the bone marrow stroma by fibrous tissue. "Consistent with this, CAR cells from PMF mice with myelofibrosis displayed reduced expression of Runx1 and Runx2 compared with control animals." (PMID 35551452, 2022). "Thus, mutations or chromosomal rearrangements involving Runx1 and/or Runx2 would not contribute to progression of myelofibrosis." (PMID 35551452, 2022).
myocarditis (1 paper, 2023). Myocarditis is a condition that is characterized by inflammation of the heart muscle (myocardium). "To find the major RUNX gene important in myocarditis pathogenesis, we compared the expression levels of RUNX2 and RUNX3." (PMID 37264110, 2023). "Although RUNX2 and RUNX3 showed upregulation of their motif activities in myocarditis, their mRNA expression levels indicated minimal changes between the two time points, highlighting the importance of ATAC-seq for understanding the gene-modulatory network." (PMID 37264110, 2023). "According to chromVAR analysis, RUNX2 and RUNX3 motifs are globally upregulated across most cell types during acute myocarditis in terms of motif activity." (PMID 37264110, 2023). "Since RUNX3 exhibits higher expression levels across all cell subpopulations than RUNX2, we propose RUNX3 as the primary TF upregulated during acute myocarditis." (PMID 37264110, 2023).
Nephroblastoma (1 paper, 2021). An embryonal neoplasm characterized by the presence of epithelial, mesenchymal, and blastema components. "The nephroblastoma overexpressed protein promotes the expression of Runx2 in osteoblasts via inhibiting AKT expression." (PMID 34398360, 2021).
Oligodontia (1 paper, 2019). The absence of six or more teeth from the normal series by a failure to develop. "Differential methylation of RUNX2 is interesting in the context of NCBRS given the clinical features of prominent interphalangeal joints, delayed dental eruption, and oligodontia in this condition." (PMID 31288860, 2019).
Osteochondroma (1 paper, 2016). A common, benign cartiliginous neoplasm arising from the metaphysis of bone. "Furthermore, the biomarkers of ossification (RUNX2, OC, AP, OPG, and RANKL) and the biomarkers of mesenchymal growth (bFGF and CTGF) were much stronger in BPOP than in osteochondroma." (PMID 26865041, 2016).
osteomyelitis (1 paper, 2021). An acute or chronic inflammation of the bone and its structures due to infection with pyogenic bacteria. "A study on osteomyelitis-associated genes indicates that chickens suffering from BCO showed downregulated level of Runt-related transcription factor (RUNX2) and secreted protein acidic and cysteine rich (SPARC) genes." (PMID 34434965, 2021). "We hypothesize that the dysbiosis of the blood microbiome results in the downregulation of RUNX2 and SPARC in BCO chickens, which further leads to osteomyelitis." (PMID 34434965, 2021).
osteosclerosis (1 paper, 2014). Abnormally high bone density. "From the early stages in our model, we observed a significant decrease in Runx2 expression with bevacizumab treatment, suggesting that bevacizumab contributes to the inhibition of osteosclerosis in the subchondral bone and inhibits osteophyte formation." (PMID 25230745, 2014).
otosclerosis (1 paper, 2022). Formation of spongy bone in the labyrinth capsule which can progress toward the stapes (stapedial fixation) or anteriorly toward the cochlea leading to conductive, sensorineural, or mixed hearing loss. "RUNX2 plays a role in bone formation and is also regulated by TGFβ1 and BMP, which have been associated with otosclerosis." (PMID 36498562, 2022).
pancreatic ductal adenocarcinoma (1 paper, 2007). An infiltrating adenocarcinoma that arises from the epithelial cells of the pancreas. "In the present study, the localisation of the Runt-related transcription factor-2 (Runx2), its transcriptional activity, as well as its regulation of expression was analysed in human pancreatic ductal adenocarcinoma (PDAC)." (PMID 17876328, 2007). "Therefore, in the present study the localisation, transcriptional activity, and regulation of Runx2 expression in human pancreatic ductal adenocarcinoma (PDAC) was analysed." (PMID 17876328, 2007).
prediabetes (1 paper, 2022). "The PBMC-isolated from 25 patients with prediabetes (25/28) expressed ALPL, BGLAP, COL1A1, and RUNX2/PPAR and the PBMC-isolated from 15 patients with normoglycemia (15/17) expressed those genes." (PMID 35237235, 2022).
sarcoidosis (1 paper, 2023). Sarcoidosis is a multisystemic disorder of unknown cause characterized by the formation of immune granulomas in involved organs. "The GCs of sarcoid-like lesion, foreign body granuloma and fibroid epulis were above 70% RUNX2-positive, while the GCs of bony callus and sarcoidosis were between 30% and 70% RUNX2-positive." (PMID 37509363, 2023). "There are no data regarding the RUNX2-expression of GCs in sarcoidosis, sarcoid like lesion, foreign body granuloma, fibroid epulis or brown tumour." (PMID 37509363, 2023).
seizure disorders (1 paper, 2025). "Associations with epilepsy or other seizure disorders, as well as syringomyelia, have been reported in the literature and might suggest conditions with chromosomal abnormalities involving additional genes beyond RUNX2." (PMID 40937214, 2025).
selenium deficiency (1 paper, 2025). A nutritional deficiency disease resulting from inadequate selenium levels in the body, which can lead to impaired function of selenoproteins essential for antioxidant defense and thyroid hormone metabolism. "Taken together, these findings suggest that selenium deficiency contributes to KBD pathogenesis by decreasing RUNX2 methylation, thereby upregulating RUNX2 expression and driving chondrocyte apoptosis." (PMID 41425094, 2025).
staphylococcus aureus infection (1 paper, 2023). An infectious process in which the bacteria Staphylococcus aureus is present. "Experiments in a mouse model revealed that G-CSF significantly downregulated the expression of Runx2, induced by Staphylococcus aureus infection in mice." (PMID 37365568, 2023).
T-cell leukemia (1 paper, 2016). A malignant disease of the T-lymphocytes in the bone marrow, thymus, and/or blood. "In the thymus, Runx2 appears to function as an oncogene because the insertion of a retroviral genome near to the Runx2 locus in mice results in its overexpression and subsequently the occurrence of T-cell leukemia." (PMID 27069802, 2016).
thrombosis (1 paper, 2022). "Staining with the VSMCs differentiation marker TAGLN was further performed, revealing that αSMA and TAGLN double‐positive VSMCs located at calcium deposits area also expressed Runx2, which suggested that VSMCs were involved in the calcification process of the venous wall after thrombosis." (PMID 35808901, 2022).
trigonocephaly (1 paper, 2021). "RUNX2 phosphorylation was present at 12 and 24 hours in trigonocephaly cells and at all time‐points in dolichocephaly cells when both IgPKD1 and MEK inhibitor were used." (PMID 33656806, 2021). "In both trigonocephaly and dolichocephaly cranial suture cells, we observed that after IgPKD1 treatment, phosphorylated RUNX2 (p‐RUNX2) was significantly increased at all time‐points." (PMID 33656806, 2021). "This positive effect of PC1 on RUNX2 activation in trigonocephaly cells was more prominent at 6 and 24 h, whereas in dolichocephaly cells, it was more prominent at 6 and 12 h." (PMID 33656806, 2021). "Interestingly, the combination of IgPKD1 and MEK inhibitor resulted in complete reversal of RUNX2 activation at 6 hours in trigonocephaly cranial suture cells." (PMID 33656806, 2021).
tuberculosis (1 paper, 2023). A chronic, recurrent infection caused by the bacterium Mycobacterium tuberculosis. "In patients with tuberculosis and accompanying ossification of the lung, RUNX2 has been shown to be present in macrophages, leading to the osteogenic differentiation of mesenchymal stem cells." (PMID 37509363, 2023). "In tuberculosis, up to 30% of GCs were RUNX2-immunoreactive, and the GCs of brown tumour were RUNX2-negative throughout." (PMID 37509363, 2023). "However, the GCs of tuberculosis have not specifically been discussed regarding their RUNX2 expression pattern." (PMID 37509363, 2023).
tumor (366 papers, 2006 to 2026). "High immunohistochemical expression of RUNX2 exhibited a significant association (p < 0.05) with high tumor grade, muscle invasion, lymph node metastasis, and advanced stage (pTNM) of the tumor." (PMID 42137676, 2026). "Multi-omics should also be utilized, including transcriptomics, chromatin accessibility, and phosphoproteomics, using RUNX2 gain- or loss-of-function experiments and validated in bone, tumor, and vascular models." (PMID 41511334, 2025). "Our analysis of clinical data in the TCGA database shows that higher MMP1 and RUNX2 levels in tumor tissues are associated with higher tumor grade and stage and poorer overall outcomes of RCC patients." (PMID 40386045, 2025). "Within this pathway, AKT1 operates as a pivotal upstream regulator of the transcription factor RUNX2, a key effector implicated in tumor progression and species, highlighting its potential as a translational target." (PMID 40862758, 2025). "High expression of RUNX2 in RCC patients is associated with higher tumor grade, stage, and poorer survival and correlates positively with MMP1 expression level." (PMID 40386045, 2025). "Using breast cancer cells, it has been shown that Runx2 is associated with tumor progression, its spread, and poor prognosis of the disease." (PMID 39595568, 2024). "On the one hand, RUNX2 is upregulated in a variety of human cancers and is closely associated with tumor metastasis." (PMID 36915153, 2023). "Evidence indicates that RUNX2 is implicated in diverse biological processes, including bone development, tumor invasion and metastasis." (PMID 37453970, 2023). "Runt‐associated transcription factor 2 (RUNX2), a main transcription factor for osteoblast differentiation and chondrocyte maturation, has high expression in a number of tumours." (PMID 37525479, 2023). "The general mechanisms underlying the role of RUNX2 in various tumour types provide directions for detailed studies on the impact of RUNX2 on the pathogenesis of HCC." (PMID 37759525, 2023). "The thyroid hormone receptor beta 1 (TRβ1) is downregulated in several human cancer cell types, which has been associated with development of an aggressive tumor phenotype and the upregulation of Runt-related transcription factor 2 (Runx2)." (PMID 36497320, 2022). "In the pathological context, Runx2 can promote metastatic properties and associated tumor-mediated osteolysis." (PMID 35884497, 2022). "Similar to past studies, SSH1 and RUNX2 were associated with the increased risk of tumor recurrence in our study." (PMID 35063012, 2022). "Similar to Runx2, high levels of autophagy and acetylated α-tubulin have been linked with resistance to anoikis, tumor progression, and metastasis, raising the question of the underlying mechanism of this phenotype." (PMID 35884497, 2022). "The participation of RUNX2 in signaling pathways associated with stem cell pluripotency suggests the participation of this TF in the differentiation of tumor stem cells (CSCs) towards tumor cells (CCs) in specific tissues." (PMID 36551878, 2022). "The proangiogenic effects of RUNX2 have been implicated in tumor progression as it has been shown to enhance endothelial cell proliferation, migration, and invasion." (PMID 36231060, 2022). "Recent studies indicate that growth factor signaling pathways, secretory factors, miRNAs, and regulatory factors such as Runx2 are promising targets in reducing bone metastatic tumor growth and bone loss in preclinical models." (PMID 34503118, 2021). "The tumor-specific SE-associated genes were enriched in important pathways, such as chordate embryonic development (RUNX2, FOXA1), regulation of cell adhesion (RUNX1, SOX2 and VEGFA), and epithelial cell differentiation (SOX9, ELF3)." (PMID 34001209, 2021). "FXR induces the expression of RUNX2 which itself causes the synthesis of bone proteins by tumor cells." (PMID 32650752, 2020).
tumor (continued). "The transcription factor RUNX2 can regulate the expressions of genes that are associated with tumor promotion, invasion, and metastasis, such as VEGF." (PMID 31405076, 2019). "In primary breast cancer, Runx2 regulates the expression of integrin α5 on tumor cells and is correlated with the risk of bone-specific metastasis." (PMID 29642534, 2018). "Within the tumour-bone microenvironment, it is known that cancer cells can express markers typically associated with bone cells, including osteopontin, osteocalcin, RUNX2 and RANKL." (PMID 28006818, 2017). "TAZ is a nuclear effector of the Hippo tumor suppressor pathway that has been implicated in promoting BC progression, but its cooperative interaction with RUNX2 in BC has yet to be elucidated." (PMID 26320173, 2015). "The RUNX2 gene located on chromosome 6p12–p21 is frequently amplified in OS and is associated with tumor growth." (PMID 26380245, 2015). "RUNX2 also regulates genes associated with tumour cell migration, metastasis and angiogenesis, such as those encoding bone sialoprotein, osteopontin, matrix metalloproteinases and vascular endothelial growth factor." (PMID 24626992, 2014). "In this cohort, which had an overall worse prognosis, high RUNX2 expression in ER/PR/HER2-negative tumours (7/38) was associated with a reduction in mean survival from 81 to 59 months." (PMID 24626992, 2014). "In NSCLC overexpression of RUNX2 has been observed in comparisons of tumor and normal tissues and was implicated with poor outcome." (PMID 25538889, 2014). "Later, we discuss the signaling pathways associated with the Wnt proteins and Runx2, and their relationship with defects in osteogenic differentiation and subsequent OS tumor development." (PMID 21437219, 2011). "On-going research is directed towards understanding the underlying story of effects of LGD1069 on Runx2 in endothelial cells and tumor cells." (PMID 21649908, 2011). "Further, analysis of sequencing data from MMRF‐CoMMpass found that POU2F2, RUNX1, and RUNX2 gene mutations were relatively rare (1.36%, 2.09%, and 0.83%, respectively) among MM patients compared to other tumor types profiled in TCGA, suggesting that their functions are preserved in MM." (PMID 40167268, 2025). "In humans and dogs, RUNX2 displays strong nuclear positivity in neoplastic cells, highlighting its central role in osteoblastic differentiation and its potential association with tumor aggressiveness." (PMID 40862758, 2025). "There could possibly be a connection between the malignancy of the tumour cells, the mineralization and the expression of the RUNX2 transcript variants." (PMID 41258582, 2025). "RUNX2 overexpression, whether at the protein or RNA level, is typically associated with aggressive tumour types, as has been reported in multiple studies." (PMID 40806771, 2025). "The inadequate regulation of RUNX2’s pro-differentiation and tumor suppressor activities may prevent MSCs predisposed to the osteoblast lineage from maturing into fully functional osteoblasts." (PMID 37370857, 2023). "We integrate and summarize the current research findings on this topic, focusing on somatic mutations of the RUNX2 gene and evidence indicating RUNX2 expression levels in different tumor types as well as the RUNX2-dependent biological effects in orchestrating cancer progression." (PMID 37108164, 2023). "On the other hand, TCF7L2 manifests an anti-tumor function by suppressing cell motility and invasiveness and by directly suppressing the activity of the pro-metastatic RUNX2–Runt-related transcription factor 2, its loss of function stimulating tumor malignancy." (PMID 37509254, 2023). "RUNX2 is a transcription factor implicated in tumor growth, invasion, and metastasis." (PMID 35110544, 2022).